CRNN (cornulin)
Diseases named in the same sentence as CRNN in open-access papers (continued):
Sharing a sentence is not in itself a finding about the gene and the disease.
eczema (1 paper, 2016). "Cornulin is a squamous cell-specific polypeptide which is downregulated in eczema and is a component of the epithelial innate immune response." (PMID 27023475, 2016).
endometrial cancer (1 paper, 2023). Primary or metastatic malignant neoplasm involving the endometrium (mucous membrane that lines the endometrial cavity). "A four-marker panel comprising of SPRR1B, CRNN, CALML3 and TXN predicted endometrial cancer with an AUC of 0.80 (0.71–0.88)." (PMID 36807337, 2023). "The four-marker panel comprising SPR1B, TXN, CRNN and CALM3 predicted endometrial cancer with an AUC of 0.78 (0.69–0.88)." (PMID 36807337, 2023).
esophageal adenocarcinoma (1 paper, 2013). A malignant tumor with glandular differentiation arising predominantly from Barrett mucosa in the lower third of the esophagus. "Although CRNN has been reported to be downregulated in esophageal adenocarcinoma (EAC) or ESCC, and genetic variants of CRNN appeared to interacte with tobacco smoking that contributes to the risk for ESCC, the precise mechanism underlying the involvement of CRNN in ESCC remains to be elucidated." (PMID 23894350, 2013).
infertile (1 paper, 2022). "Finally, six proteins were found to be unique in the infertile group; these were neuroblast differentiation-associated protein (AHNAK), isoaspartyl peptidase/L-asparaginase (ASRGL1), UMP-CMP kinase (CMPK1), phosphoglucomutase-1 (PGM1), cornulin (CRNN), and suprabasin (SBSN)." (PMID 35719135, 2022).
invasive carcinoma (1 paper, 2024). A carcinoma that is not confined to the epithelium, and has spread to the surrounding stroma. "Moreover, Cornulin expression inversely correlates with the severity of dysplastic changes in the premalignant lesions that precede these invasive carcinomas." (PMID 39336714, 2024).
lymph node metastasis (1 paper, 2022). "Cornulin was found to be significantly downregulated in primary tumors with lymph node metastasis, a major contributor to cSCC progression to the advanced clinical stages." (PMID 36721574, 2022). "Detection assays to measure Cornulin expression in cSCC primary tumors might aid in determining the nodal status in these patients and possibly help determine cases of occult lymph node metastasis or micrometastasis." (PMID 36721574, 2022).
oral epithelial dysplasia (1 paper, 2024). "Immunohistochemical analysis of the relative Cornulin expression in high-grade oral epithelial dysplasia, low-grade oral epithelial dysplasia, normal oral mucosa, and OSCC revealed that the normal oral mucosa has the highest intensity of staining." (PMID 39336714, 2024). "Importantly, the staining intensity decreased as the severity of oral epithelial dysplasia increased, while OSCC samples showed the least amount of Cornulin immunoreactivity in this progression spectrum." (PMID 39336714, 2024).
skin cancer (1 paper, 2022). "Future clinical studies are needed to help establish Cornulin’s role in enhancing the predictive power of histopathological examination and improving survival rates for patients suffering from this type of skin cancer." (PMID 36721574, 2022).
squamous intraepithelial lesions (1 paper, 2024). "Additionally, Cornulin expression correlated inversely with the severity of dysplasia, which indicates the risk for malignant transformation in the premalignant squamous intraepithelial lesions." (PMID 39336714, 2024). "Cornulin expression showed a stepwise downregulation from the normal cervical epithelium to the squamous intraepithelial lesions (SIL) and to the cervical squamous cell carcinoma." (PMID 39336714, 2024).
tumor (21 papers, 2013 to 2025). "Cornulin overexpression has also been associated with tumor growth inhibition in immunocompromised mice." (PMID 39336714, 2024). "The tumor-suppressive mechanism of CRNN was associated with its role in cell cycle arrest at G1/S checkpoint by upregulating expressions of P21WAF1/CIP1 and Rb." (PMID 23894350, 2013). "Cornulin, encoded by the CRNN gene located on chromosome 1q21 locus, is a 495 amino acid protein that belongs to the family of S100 fused-type proteins and is postulated to possess tumor suppressor characteristics." (PMID 36561600, 2022). "Destruction of structural protein COL1A2, and loss of tumour related proteins CRNN and DCN support the speculation that all three are involved in a pathway for TSCC genesis." (PMID 33889206, 2021). "Studies documenting relapse rates reported correlations between lower disease-free survival and increased Cyclin D1 or VEGF expression, and between increased tumor recurrence and decreased Cornulin expression or increased HRAS expression." (PMID 41465166, 2025). "Although its precise molecular mechanisms remain to be fully elucidated, studies have suggested that Cornulin functions as a tumor suppressor, particularly by arresting the cell cycle at the G1/S transition." (PMID 41465166, 2025). "In line with the findings observed in the laboratory setting, in vivo overexpression of CRNN significantly promoted tumor growth." (PMID 39292704, 2024). "Cell cycle analysis suggests that Cornulin arrests the cell cycle at the G1/S transition in collaboration with two other tumor suppressors, Retinoblastoma (Rb) and P21WAF1/CIP1." (PMID 39336714, 2024). "Since Cornulin is less abundant in dysplastic cervical tissues, the oxidative damage to Cornulin is likely to further impair its functions, such as the tumor-suppressor function, in these premalignant lesions." (PMID 39336714, 2024). "Using a mouse xenograft model, we demonstrated that the inhibition of CRNN led to a decline in cSCC tumor growth in a living organism, providing evidence of CRNN’s involvement in cSCC occurrence and development." (PMID 39292704, 2024). "Cornulin, encoded by the CRNN gene on chromosome 1q21, is a 495 amino acid protein that belongs to the S100 fused-type protein family and is reported to have tumor-suppressing properties." (PMID 37185759, 2023). "In our study, we predicted that Cornulin expression patterns are likely to reflect the multi-step carcinogenesis process of cSCC, given its role as a tumor suppressor." (PMID 36721574, 2022). "Loss of CRNN expression has been associated with advanced tumor stage, whereas high expression of KLK5 has been positively correlated with tumor invasion." (PMID 35976902, 2022). "CRNN was found significantly downregulated in TSCC in a genome-wide transcriptomic study on 53 primary tumour tissues." (PMID 33889206, 2021). "In conclusion, our findings demonstrate that CRNN is a tumor suppressor gene that plays a critical tumor suppressive role in ESCC." (PMID 23894350, 2013). "In the present study, tumor suppressive function of CRNN was characterized by both in vitro and in vivo assays including cell growth, foci formation and soft agar assays, and tumor formation in nude mice." (PMID 23894350, 2013). "In conclusion, we demonstrate that CRNN is a potential tumor suppressor in ESCC via arresting cell cycle progression at G1/S checkpoint by upregulating P21WAF1/CIP1 and Rb." (PMID 23894350, 2013). "Additionally, we examined the presence of CRNN protein in tissue samples from nude mouse tumor tissues using immunohistochemical staining." (PMID 39292704, 2024). "The study also correlated low Cornulin expression with the largest tumor dimension." (PMID 39336714, 2024). "While the intricate molecular mechanisms of Cornulin’s role in tumorigenesis are still unknown, it has been shown to exert significant tumor-suppressive effects." (PMID 39336714, 2024).
tumor (continued). "Moreover, the gradual downregulation in Cornulin expression correlates with the stepwise progression to neoplasia in these lesions." (PMID 39336714, 2024). "Our results suggest that cornulin may have a role as a potential tumor suppressor, as its expression decreases as the cells progress from normal to SIL and SCC." (PMID 37185759, 2023). "Cornulin has been proposed as a tumor suppressor gene, controlling pathways involved in cancer cell proliferation, migration, invasion, and apoptosis, however, its mechanism of action is still unknown." (PMID 37185759, 2023). "Additionally, we plan on re-examining the Cornulin expression patterns after implanting these human tumor cell lines into immunocompromised mice." (PMID 36620799, 2022). "Cornulin, encoded by the CRNN gene, is a 495 amino acid protein belonging to the family of S100 fused-type proteins, is located on chromosome 1q21 locus, and has tumor suppressor characteristics." (PMID 36620799, 2022). "However, CRNN is expressed −34.28× less in EAC tumor cells compared to normal esophageal epithelial cells according to our findings (P < 0.0001), adding CRNN as a viable oncoprotein for EAC as well." (PMID 29868478, 2018). "A better understanding of the tumor suppressive role of CRNN will significantly improve our knowledge in the development of ESCC, and may lead to a more effective management of ESCC patients with the inactivation of CRNN." (PMID 23894350, 2013). "Therefore, the expression of CRNN protein will presumably help maintain the barrier function in squamous epithelium in response to injury and function as a tumor suppressor." (PMID 23894350, 2013). "In the present study, the tumor suppressive function of CRNN has been clearly demonstrated, however, the molecular mechanism of CRNN in ESCC development remains unclear." (PMID 23894350, 2013). "Notably, Cornulin expression decreases within cSCC as the tumor histopathological grade increases." (PMID 39336714, 2024). "The tumor subtypes reflected by the patient-derived ex vivo cultures were validated by qPCR analysis of keratinization (CNFN, CRNN), basal (KRT5, KRT6), and luminal markers (KRT7, GATA3)." (PMID 41387887, 2025). "Subsequent mechanistic studies confirmed that the overexpression of Cornulin in ESCC cell lines inhibits cellular proliferation and tumor formation in patient-derived xenograft models (PDX)." (PMID 39336714, 2024). "Conversely, cornulin exhibited the strongest expression in the normal cervix and lowest in SCC, supporting its role as a tumor suppressor and potential biomarker for disease progression." (PMID 37185759, 2023). "Functional studies involving TAGLN2 knockdown and CRNN overexpression demonstrated their inhibitory effects on ESCC cell proliferation, colony formation, organoid growth, and ESCC PDX tumor growth." (PMID 37553345, 2023). "We performed meta-analysis on 8 microarray studies and identified six significantly up- (PLAU, FN1, CDCA5) and down-regulated (CRNN, CLEC3B and DUOX1) genes which were subsequently quantified by RT-qPCR in 100 HNSCC patient margin and core tumour samples." (PMID 31443700, 2019). "Moreover, the overexpression of Cornulin in LSCC cell lines inhibited their growth and their progression through the cell cycle, attenuated their migration and invasion, and inhibited their tumor formation when implanted subcutaneously into nude mice." (PMID 39336714, 2024). "Our study focused on quantitative analysis of Cornulin expression in established cell lines representing the successive steps of OSCC tumor progression, namely non-cancerous, dysplastic, locally invasive, and metastatic oral lesions." (PMID 36620799, 2022). "Specifically, primary tumors with metastasis to regional lymph nodes (N1) exhibited 9.5-fold decrease in Cornulin immunoreactivity compared to the primary tumor samples without lymph node involvement (N0)." (PMID 36721574, 2022).
tumor (continued). "Specifically, primary tumors with metastasis to regional lymph nodes (N1) showed an approximately 10-fold decrease in Cornulin immunoreactivity compared to the tumor samples without lymph node involvement (N0)." (PMID 36721574, 2022). "Our data revealed that TAGLN2 knockdown or CRNN overexpression inhibited ESCC PDX tumor growth, leading to reduced tumor volume and tumor weight, without any adverse effects on the mice body weight." (PMID 37553345, 2023).
cancer (16 papers, 2007 to 2025). A tumor composed of atypical neoplastic, often pleomorphic cells that invade other tissues. "Among the identified FRGs, MYBPH, SOST, SPRR2A, and CRNN were notably upregulated in the high-risk group, implying their potential involvement as cancer-promoting genes in BLCA development." (PMID 38172792, 2024). "CRNN overexpression has been found to enhance cell growth and prevent cells from undergoing natural cell death, and the cancer-promoting effects of CRNN are linked to AKT activation." (PMID 39292704, 2024). "Cornulin is a newly discovered member of the “fused gene” family and the product of the novel gene c1orf10, an oesophageal-specific and cancer-associated gene located on 1q21." (PMID 36064415, 2022). "Interestingly, circulating Cornulin levels in the plasma showed a strong linear dose-dependent correlation with the use of Swedish moist snuff (snus), a suspected risk factor for cancer development." (PMID 39336714, 2024). "Based on all these findings, we can postulate a protective role for Cornulin in the oral mucosa in response to DNA-damaging risk factors, such as tobacco and alcohol use, and a mechanism by which Cornulin downregulation allows for these malignant tumors to occur and progress to advanced stages." (PMID 39336714, 2024). "We validated our findings by immunohistochemical staining for Cornulin, confirming heterogeneous expression patterns in squamous epithelium and carcinoma tissue." (PMID 41418981, 2025). "The functions of TAGLN2 and CRNN in different types of cancer have been studied in various literature." (PMID 37553345, 2023). "Our study observed that cornulin expression reduced as cells became less differentiated in the dysplastic and cancer phases." (PMID 37185759, 2023). "Cornulin was identified to have cancer-promoting effects in SCC and may reflect spatial differences in cell differentiation." (PMID 41418981, 2025). "In a separate study, Cornulin and Keratin 4 were selected from a group of protein biomarkers that are differentially expressed between normal and cancer tissues, and their expression was examined in the surgical margins of 46 patients with head and neck squamous cell carcinoma." (PMID 39336714, 2024). "More studies are needed to shed light on the metabolic and signaling pathways that might involve Cornulin, as well as offer insights on how to utilize this knowledge to improve clinical outcomes for patients afflicted with these common types of human cancers." (PMID 39336714, 2024). "Moreover, SPARC-like protein 1 (SPARCL1), IQGAP1, BPIFA1, and cornulin are potential candidate proteins abnormally expressed in multiple types of cancers, especially LC." (PMID 36064415, 2022). "An adjusted (Tukey) box-plot analyses showed evidence of lower concentrations of SPRR1B, CRNN, TXN and FABP5 in cancers compared to controls." (PMID 36807337, 2023). "In all non-cancer oral mucosal tissues, epithelial cells showed strong (IRS = +9) cytoplasmic staining with anti-CRNN antibody in the epithelium." (PMID 33889206, 2021). "In this study, we explore the expression of CRNN, COL1A2 and DCN in a well-characterised bank of non-cancer disease and pN− and pN+ TSCC tissues with extensive records on use of addictive agents." (PMID 33889206, 2021). "CRNN, also known as squamous epithelial heat shock protein 53, was highly up-regulated in ND (247.78 fold) and NB but not T, suggesting that the processes of calcium binding, mucosal/epithelial immune response and epidermal differentiation are not altered in cancer." (PMID 22280838, 2012).
infection (3 papers, 2007 to 2024). The state of being infected such as from the introduction of a foreign agent such as serum, vaccine, antigenic substance or organism. "In head and neck squamous cell cancer, the downregulation of cornulin may cause the squamous epithelia to be more susceptible to infection and eventually lead to carcinogenesis." (PMID 37185759, 2023).
CRNN also shares sentences with these, for which no sentence is quoted: head and neck cancer (2 papers); basal cell carcinoma (1); chronic gastritis (1); colorectal cancer (1); diffuse large B-cell lymphoma (1); Hyperkeratosis (1); Insulin resistance (1); metastasis (1); metastatic cancer (1); pancreatic adenocarcinoma (1); stenosis (1); thyroid cancer (1).